ACE (angiotensin I converting enzyme)
Diseases named in the same sentence as ACE in open-access papers (continued):
Sharing a sentence is not in itself a finding about the gene and the disease.
heart failure (continued). "In addition, TG9 mice exhibit many of the salient molecular and functional changes observed in human heart failure including elevated brain natriuretic peptide levels and a positive response to beta blockers and ACE inhibitors." (PMID 21359201, 2011). "There is therefore insufficient evidence to answer the question whether the addition of ARBs to standard therapy with ACE inhibitors and beta-adrenergic antagonists offers any benefit in patients with heart failure." (PMID 20376345, 2010). "In most patients hemodynamically important valvular dysfunction can be controlled with conservative treatment (i.e immunosuppression, anticoagulation, endocarditis profylaxis, and specific heart failure treatment including ACE-inhibitors, beta-blockers, diuretics)." (PMID 20331896, 2010). "Results of CIBIS III support a free choice, based on the physician’s individual judgment with each patient, as to whether a beta-blocker or an ACE inhibitor should be used first in patients with heart failure." (PMID 21150007, 2010). "Thus therapy for heart failure is usually started with an ACE inhibitors and β-blockers added later." (PMID 21150007, 2010). "Thus, treatment decisions favouring either therapy cannot be based on solid evidence due to the lack of any cost-utility analysis incorporating quality of life data comparing combination to ACE inhibitor therapy alone in patients with heart failure." (PMID 20376345, 2010). "Combination therapy with ARBs and ACE inhibitors reduces admissions for heart failure in patients with congestive heart failure when compared to ACE inhibitor therapy alone, but does not reduce overall mortality or all-cause hospitalization and is associated with more adverse events." (PMID 20376345, 2010). "First, despite maximization of pharmacologically mediated therapeutic regimens which include ACE inhibitor therapy, patients with heart failure continue to develop pulmonary arterial hypertension via a reactive component, most likely mediated through pulmonary arterial endothelial dysfunction." (PMID 20957051, 2009). "Thus during the treatment of heart failure, these results are consistent with both ACE-inhibitor and ARB therapy decreasing Ang II mediated signaling to alter the vascular phenotype by preventing the fall in LZ+ MYPT1 expression." (PMID 19357768, 2009). "Following the discontinuation of trastuzumab, 6 patients have recovered normal LV systolic function, while 4 patients have persistent LV dysfunction at six month followup, despite appropriate heart failure medications including ACE inhibition and beta blockade." (PMID 18272009, 2008). "A German study of chronic cardiac care found that heart failure management according to current guidelines, use of beta-blockers and ACE inhibitors, and invasive cardiac examination was performed significantly less in the rural CH than in the metropolitan heart center." (PMID 17184517, 2006). "These clinical findings are compatible with experimental findings showing that ACE-inhibition could attenuate heart failure induced atrial functional remodeling and fibrosis in dogs." (PMID 15667649, 2005). "Those who used the HFICT were older, and more likely to be female, to have idiopathic dilated cardiomyopathy, to have a worse functional class, and to be on proven medications for heart failure such as Angiotensin Converting Enzyme (ACE) inhibitors and beta-blockers." (PMID 15829480, 2005). "For patients with heart failure and reduced ejection fraction (HFrEF),angiotensin receptor–neprilysin inhibitors (ARNIs) such as sacubitril/valsartanhave demonstrated superiority over ACE inhibitors in reducing cardiovascularmortality and hospitalizations, as shown in the PARADIGM-HF trial." (PMID 41356289, 2025). "Consequently, although ACE inhibitors and ARBs are effective in reducing heart failure and cardiovascular events, their effects on the reduction of non-cardiovascular mortality remain unknown and require additional study." (PMID 41527634, 2025).
heart failure (continued). "For patients with heart failure with reduced ejection fraction (HFrEF), treatment with sacubitril-valsartan, an angiotensin receptor−neprilysin inhibitor, has become increasingly preferred over angiotensin-converting enzyme inhibitors (ACE-Is) and angiotensin II receptor blockers (ARBs)." (PMID 39951312, 2025). "Given the promising results of TDI in early detection, future studies could explore the potential impact of heart failure medications, such as ACE inhibitors (ACEi) or beta-blockers, on improving TDI parameters and overall cardiac function in patients receiving Adriamycin." (PMID 40773489, 2025). "In a Brazilian cohort of 402 patients with positive serology for CD, in a case-control study we used PCR for genotyping the ACE rs4646994 I/D and AGTR1 rs5182C>T, rs275653 -119C>T, rs2131127A>G and rs5186 +1166A>C polymorphisms to evaluate association with CARD and progression to heart failure." (PMID 39591456, 2024). "Furthermore, medication effects, particularly from commonly used ACE inhibitors and spironolactone in heart failure management, could have influenced echocardiographic indices." (PMID 39409756, 2024). "In addition, therapy of heart failure was commenced in the form of ACE inhibitors." (PMID 39337571, 2024). "In addition, a study has shown that the beneficial effects of ACE inhibitors in heart failure may be partially due to anti-inflammatory and neutropenia effects." (PMID 38233747, 2024). "RAAS inhibitors, including angiotensin-converting enzyme (ACE) inhibitors and angiotensin receptor blockers (ARBs), decrease the adverse effects of angiotensin II and aldosterone, which are major contributors to cardiac remodeling, fibrosis, and cellular dysfunction in heart failure." (PMID 39766241, 2024). "We also did not account for associated therapies such as ACE inhibitors or beta-blockers, which could have better identified the population of patients with heart failure." (PMID 39523415, 2024). "Another population that may benefit from reduced K+ levels is heart failure patients, who may not be prescribed ACE inhibitors due to hyperkalemia exacerbation or the risk of new hyperkalemia." (PMID 38406030, 2024). "Indeed, anthracycline-induced cardiotoxicity (AIC) fares among the worst types of cardiomyopathy, and may only slowly and partially respond to standard heart failure therapies including β-blockers and ACE inhibitors." (PMID 36970353, 2023). "In RADIANCE trial, 178 heart failure patients with ejection fraction of < 35% and NewYork Heart Association (NYHA) class II–III symptoms on a stable regimen of digoxin, diuretics, and an ACE-inhibitor (captopril or enalapril) were randomized to withdrawal or continuation of digoxin for 12 weeks." (PMID 35619305, 2023). "In addition, ACE-inhibitor associated angioedema is apparently not relevant in the treatment of heart failure, reinforcing the view that race as a criterion is unjustified." (PMID 34508156, 2022). "ACE inhibitors were also discontinued in patients with chronic coronary syndromes or heart failure based on initial speculations that the use of ACE inhibitors, leading to increased expression of ACE2, which could potentially facilitate infection with COVID-19." (PMID 35409640, 2022). "However, it is not clear whether physical activity and ACE-I could synergistically modulate ACE/ACE-2 balance in the course of heart failure (HF)." (PMID 34163362, 2021). "For the management of heart failure, an intravenous loop diuretic agent, furosemide, was started first, followed by initiation of a beta-blocker, oral bisoprolol, at 1.25 mg daily, as well as an angiotensin-converting enzyme (ACE) inhibitor, oral perindopril, at 2 mg daily." (PMID 34766014, 2021).
heart failure (continued). "Medications that target ACE and angiotensin receptors, such as angiotensin-converting enzyme inhibitors (ACEIs) and angiotensin receptor blockers (ARBs), respectively, are widely used as antihypertensive agents and therapies for patients with heart failure and diabetic complications." (PMID 34285715, 2021). "In addition, in rats with post-MI heart failure, a combination of canrenone, the active metabolite of potassium canrenoate and ramipril, angiotensin-converting enzyme (ACE) inhibitor, attenuated LV dilation and interstitial remodeling and improved cardiac function compared solo-treatment." (PMID 34381364, 2021). "For instance, upon ingestion of angiotensin-I-converting enzyme (ACE) inhibitors patient may encounter severe or mild adverse effects, such as cough, headache, diarrhea, dizziness, fatigue, angioedema, hyperkalemia or, in rare cases, renal and cardiac failure." (PMID 31671730, 2019). "However, once heart failure develops, angiotensin converting enzyme inhibitors (ACE inhibitors), beta-blockers and spironolactone may be considered." (PMID 29582880, 2018). "However still there was implication that immune suppressive intervention, including glucocorticoid pulse therapy, in addition to palliative therapy against heart failure with diuretics, a β-blocker, and an ACE inhibitor, markedly improved her CI as well as the skeletal myositis." (PMID 28316854, 2017). "In addition, the complementary pharmacologic effects suggest that HNO could augment β-blocker and ACE inhibitor effects in the treatment of heart failure." (PMID 29209225, 2017). "In the PARADIGM-HF study of 8442 patients with heart failure and reduced ejection fraction (HFrEF), LCZ696 reduced the primary endpoint of cardiovascular death or heart failure hospitalization by 20% and reduced death due to any cause by 16% (both p<0.001) compared with the ACE-inhibitor enalapril." (PMID 26352157, 2015). "Several subsequent multicenter clinical trials, using other ACE inhibitors or the newer ARBs, confirmed the initial findings thereby demonstrating their beneficial effects on ventricular remodeling, reduction in the end-stage events of cardiac failure, and repeated myocardial infarction." (PMID 24600438, 2014). "There are many evidence based indications for use of ACE inhibitors and ARAs and national guidelines recommend treatment with them for a number of chronic conditions including hypertension, chronic kidney disease with proteinuria, and heart failure with left ventricular dysfunction." (PMID 24223154, 2013). "An absence of lowering effect on systolic blood pressure may be particularly appealing to clinicians who find their patients with heart failure often have relatively low blood pressure on a combination of ACE-inhibitors, beta blockers, spironolactone or eplerenone, and loop diuretics." (PMID 22811735, 2012). "Indeed, ACE-inhibition improves pulmonary diffusion in heart failure." (PMID 23365739, 2012). "In the VALIANT study, addition of ARB valsartan to ACE inhibitor resulted in similar degree of post-MI left ventricular (LV) remodeling compared to either drug alone, although in the Val-HeFT study, LV remodeling in heart failure was more favorable in the combination therapy group." (PMID 22108275, 2011). "It has been demonstrated that angiotensin-converting enzyme (ACE) inhibitors and angiotensin receptor blockers (ARBs) can stop heart failure from getting worse, and beta-blockers can help reduce the workload on the heart and stop arrhythmias." (PMID 41018340, 2025). "Additionally, ACE inhibitor therapy can lead to hypotension through other potential mechanisms, such as an increase in vasodilatory prostaglandins or a decrease in total peripheral resistance, particularly in cases where cardiac output remains unchanged due to heart failure." (PMID 40137155, 2025). "The use of ACE inhibitors and ATR1 blockers has been extensively studied in diabetic patients with heart failure." (PMID 40149735, 2025).
heart failure (continued). "Angiotensin-converting enzyme inhibitors (ACE inhibitors) are important for blood pressure therapy and for the basic therapy of heart failure." (PMID 40846813, 2025). "This can result from, for example, heart failure, or the use of Angiotensin-Receptor Blocking (ARB) or Angiotensin-Converting Enzyme (ACE) inhibitor therapies, respectively." (PMID 40131721, 2025). "Enalapril is an angiotensin-converting enzyme (ACE) inhibitor, which is strongly recommended as first-choice therapy in patients with heart failure." (PMID 38362882, 2024). "The overall benefits of thiazide or thiazide-like diuretics compared to ACE inhibitors that were observed in MDCR, in terms of acute MI and hospitalization with heart failure, were mainly driven by patients with predicted acute MI risk above 1.5%." (PMID 36991144, 2023). "In comparison with enalapril, an angiotensin-converting enzyme (ACE) inhibitor, it has a better effect in reducing the incidence rate and mortality rate of heart failure patients with decreased ejection fraction." (PMID 36836477, 2023). "Moreover, these individuals may benefit from the initiation of pharmacological treatments such as ACE inhibitors and angiotensin II type 1 receptor antagonists capable to ameliorate endothelial dysfunction and, possibly, to reduce the progression to heart failure." (PMID 37755541, 2023). "Most importantly, only 38.1% and 25.9% of our patients were taking some doses of a beta blockers and angiotensin converting enzyme (ACE) inhibitors, respectively, against a high frequency of heart failure, 64.5%." (PMID 35813679, 2022). "In fact, the combination of ACE inhibitors with AT1R blockers, eprosartan has been reported to improve cardiac output in patients with severe heart failure." (PMID 36359731, 2022). "Since drug therapy for chronic heart failure, especially ACE inhibitors and β-blockers, can also treat CSB itself, drug treatment for heart failure and optimization thereof should be performed in accordance with heart failure guidelines." (PMID 38469064, 2022). "A decrease in the angiotensin-converting enzyme (ACE)/angiotensin (Ang) II/Ang II type 1 receptor (AT1) axis of RAS provides protection from pathological cardiac hypertrophy and subsequent heart failure." (PMID 34501285, 2021). "Certainly, the optimization of therapy for heart failure after CRT implantation also plays an important role, as there is evidence that ß-blockers, some ACE inhibitors, and aldosterone antagonists lead to an increase in vagal tone." (PMID 34573751, 2021). "Therefore, in tumor patients infected with SARS-CoV-2, the downregulation of ACE2 levels might cause an imbalance in the RAS system and activate the ACE-Ang II-AGTR1 axis, which would likely aggravate the clinical symptoms of tumor patients with heart disease and even induce heart failure." (PMID 34671200, 2021). "Inhibition of ACE enzyme and ang II receptor improved ANP levels as well as cGMP levels in plasma and urine in a rat model of shunt-induced heart failure." (PMID 32781523, 2020). "Beta-blockers, ACE inhibitors, ARB and mineralocorticoid/aldosterone receptor antagonists (MRAs) convincingly reduce mortality and morbidity in heart failure patients with reduced systolic function in the general population." (PMID 32977752, 2020). "For the past 50 years, therapy based on antagonism of beta adrenergic receptors, angiotensin converting enzyme (ACE), and/or AT2 receptors has been the staple for heart failure (HF) treatment." (PMID 32116711, 2020). "As diuretic is one of the medical treatment regimens for heart failure, for ongoing heart failure status in DMD children, the initial treatment protocol should include diuretics, ACE inhibitor, and inotropic agents, which helped the myocardial protection." (PMID 33266491, 2020). "Current treatments like Angiotensin-Converting Enzyme (ACE) inhibitors and beta-blockers can, at the best, slow the progression of heart failure and death." (PMID 31792327, 2019).
heart failure (continued). "The PARADISE-MI evaluates SAC/VAL vs. ACE inhibitor treatment in post-AMI patients with LV systolic dysfunction in order to compare their effects on cardiovascular death and heart failure hospitalization." (PMID 30962467, 2019). "ACE: Angiotensin-converting enzyme; BUN: Blood urea nitrogen; ED: Emergency department; HF: Heart failure; ICD: Implantable cardioverter defibrillator." (PMID 31245189, 2019). "In these cases, drugs such as angiotensin-converting enzyme (ACE) inhibitors, angiotensin II receptor blockers (ARBs), beta-blockers, and aldosterone antagonists are prescribed as a standard therapy to treat heart failure in these patients." (PMID 31394715, 2019). "The Chinese herbal formula SNT could improve left ventricular systolic function in heart failure after myocardial infarction in rats and decreased the level of Plasma Renin, Angiotensin II, and Aldosterone, as well as downregulating the protein and gene level of ACE and AT1R." (PMID 30050591, 2018). "Increased vascular angiotensin-converting enzyme (ACE) activity and oxidative stress are present in young Syrian cardiomyopathic hamsters (SCH) before the clinical manifestation of heart failure (HF)." (PMID 27420103, 2016). "Angiotensin-converting enzyme (ACE) inhibitors improve left ventricular (LV) remodelling and outcome in heart failure and hypertensive heart disease." (PMID 25796267, 2015). "However, indirect studies showed that beta-blockers, ACE inhibitors, ARBs, and aldosterone antagonists are useful for modifying the harmful effects of the sympathetic nervous system and renin-angiotensin-aldosterone system and are the preferred drugs in patients with heart failure." (PMID 26893917, 2015). "Enalapril is an angiotensin-converting enzyme (ACE) inhibitor used in the treatment of primary hypertension, heart failure, left ventricular dysfunction, and chronic kidney failure." (PMID 26607661, 2015). "Therefore, in this investigation, we aimed to elucidate whether oral administration of ACE inhibitors may effectively reduce cardiovascular responses to acute stress in the postinfarct heart failure, during chronic stress and during combination of these two challenges." (PMID 25045668, 2014). "With regard to standard therapy for heart failure, our analysis revealed that more IMP obtained beta-blockers and/or ACE inhibitors/angiotensin-receptor-blockers (ARB) compared to the NIMP." (PMID 23812247, 2013). "In the ALiskiren Observation of heart Failure Treatment (ALOFT) study, patients with stable HF, and treated with an ACE inhibitor (or ARB) and β-blocker were randomized to once-daily, double-blind treatment with aliskiren 150 mg or placebo." (PMID 23866091, 2013). "A series of landmark trials with ACE inhibitors in patients with LVD or HF such as VALsartan in Acute myocardial INfarction (VALIANT), Valsartan in Heart Failure Trial (Val-HeFT) and others have reported reductions in CV mortality and morbidity." (PMID 23866091, 2013). "Three of 8 patients had cardiac failure according to ECHO and were supplemented with Se in addition to digoxin and ACE inhibitors." (PMID 23125858, 2012). "In the heart, an increased activity of the classical axis of the renin-angiotensin system (RAS) composed by angiotensin-converting enzyme (ACE), Ang II, and AT1 receptor leads to ventricular hypertrophy, heart failure, and fibrosis." (PMID 22482038, 2012). "There is a need for randomised controlled trials evaluating the effect of adding ARBs to patients taking ACE inhibitor therapy and beta-adrenergic antagonists for the treatment of heart failure in order to see whether ARBs offer any additional benefit to current standard therapy for heart failure." (PMID 20376345, 2010). "At present, peripartum cardiomyopathy is treated according to the guidelines for dilated cardiomyopathy with angiotensin converting enzyme (ACE) inhibitors, beta-blockers and diuretics (standard therapy for heart failure)." (PMID 20202212, 2010).